IGFBP2 (insulin like growth factor binding protein 2)
Diseases named in the same sentence as IGFBP2 in open-access papers (continued):
Sharing a sentence is not in itself a finding about the gene and the disease.
Hyperinsulinemia (16 papers, 2010 to 2026). An increased concentration of insulin in the blood. "IGFBP-1 and IGFBP-2 levels are inversely associated with insulin levels, which suggests that chronic hyperinsulinemia could depress binding protein interaction and thus increase free IGF-I." (PMID 20148110, 2010). "On the other hand, IGFBP-1 and IGFBP-2 have a well-known role in metabolic regulation, maintaining blood glucose levels, insulin sensitivity, glucose intolerance, and hyperinsulinemia." (PMID 26858687, 2016). "Hyperinsulinemia can also decrease the production of insulin-like growth factor-binding protein 1 (IGFBP-1) in the liver and other organs and is linked to lower plasma insulin-like growth factor binding protein-2 (IGFBP-2) levels." (PMID 35270737, 2022). "The derived network revealed a direct inverse effect of basal hyperinsulinemia on Insulin-like Growth Factor Binding Protein-1 (IGFBP-1), which then positively affects IGFBP2." (PMID 40502600, 2025). "As mentioned, hyperinsulinemia leads to an increase in IGF-1 bioactivity through inhibition of IGFBP-1 and IGFBP-2." (PMID 34208601, 2021). "Hyperinsulinemia is able to reduce IGF binding protein- (IGFBP-) 1 and IGFBP-2, which regulate levels of IGFs." (PMID 29706998, 2018). "Chronic hyperinsulinemia inhibits the production of IGF-binding protein 1 (IGFBP-1) and IGFBP-2, which results in the increased bioavailability of IGF-1." (PMID 25402501, 2014). "As hyperinsulinemia decreases IGF-binding protein–1 (IGFBP-1) and IGFBP-2 levels, insulin may reduce certain IGFBP levels and increase bioavailable IGF levels to indirectly enhance the IGF–IGF-1R signaling pathway." (PMID 36213272, 2022). "However, in patients with hyperinsulinemia not only is more insulin secreted, but the production of IGFBP-1 and IGFBP-2 is diminished, therefore permitting a higher concentration of active IGF-1 which can stimulate insulin receptors (IR) on endometrial tumor cells." (PMID 35439978, 2022). "In addition, hyperinsulinemia leads to decreased hepatic synthesis of insulin-like growth factor (IGF)-binding protein 1 (IGFBP-1) and protein 2 (IGFBP-2) and may result in increased bioactivity of IGF-I, which directly induces the development of CRC due to its mitogenic and antiapoptotic actions." (PMID 31681585, 2019). "In patients without hyperinsulinemia, IGF binding proteins (IGFBP-1 and IGFBP-2) control the amount of active IGF-1 that can act on cells to induce cell proliferation." (PMID 35439978, 2022).
hepatocellular carcinoma (14 papers, 2012 to 2025). A malignant tumor that arises from hepatocytes. "For example, in hepatocellular carcinoma, IGFBP2 facilitates the EMT process by activating the Wnt/β-catenin signaling pathway." (PMID 40728947, 2025). "IGFBP2 or 3 had a high AUC (>0.8) for healthy controls versus cholangiocarcinoma and hepatocellular carcinoma." (PMID 27579675, 2016). "Significant AUC values of IGFBP2 were observed in gastric cancer, cholangiocarcinoma, hepatocellular carcinoma, colon cancer and duodenal cancer against healthy controls." (PMID 27579675, 2016). "With these IGF antibody arrays, we measured the expression levels of 10 members of IGF signal family and found that IGF-2R and IGFBP-2 were increased in hepatocellular carcinoma (HCC) tissues compared with adjacent tissues." (PMID 23071652, 2012). "Through a comparative analysis of gene expression data from hepatocellular carcinoma samples with high vs. low EMP2 expression, we identified 28 genes associated with autophagy, such as IGFBP2 and BNIP3, suggesting a potential linkage between EMP2 and autophagy in liver cancer." (PMID 39866225, 2025). "Two reports found IGFBP-2 to regulate EMT in hepatocellular carcinoma (HCC)." (PMID 41226289, 2025). "The levels of IGFBP2 determined by RPPA were also increased in gastric cancer, cholangiocarcinoma, hepatocellular carcinoma, and colon cancer compared to healthy controls, which corresponded to the result of LC-MS/MS." (PMID 27579675, 2016). "The other 6 proteins tested were chosen because of their reported involvement in liver diseases (e.g. GDF15, which has been shown to be involved in liver disease and hepatocellular carcinoma) and other cancers (as is the case for CEA, IGFBP2, B2M, PDGF-Rb and OPN)." (PMID 30220970, 2018). "Furthermore, IGFBP2 or 3 exhibited a relatively low AUC (<0.8) for discriminating IDACP from other malignancies, except hepatocellular carcinoma in the case of IGFBP3." (PMID 27579675, 2016). "Finally, the positive effects of recombinant IGFBP2 were not restricted to HEK293-2 cells, but were also identified in hepatic carcinoma cells (HuH-7)." (PMID 33668197, 2021). "However, the AUC values of IGFBP2 and 3 between most malignancies and IDACP were not so high (AUC < 0.8), except in the case of IGFBP3 for hepatocellular carcinoma, suggesting that these proteins have limited specificity for IDACP diagnosis." (PMID 27579675, 2016).
Hyperglycemia (13 papers, 2017 to 2025). An increased concentration of glucose in the blood. "ADIPOQ and IGFBP2 were associated with the four incident components with significant results namely increased waist circumference, hypertriglyceridemia, hyperglycemia and increased blood pressure." (PMID 34016094, 2021). "One study in this context reveals that hyperglycemia significantly reduces docetaxel-induced apoptosis in PCa cell lines, which is intricately linked to the glucose-induced upregulation of IGFBP2, which is further regulated by SIRT1 through histone acetylation at the IGFBP2 promoter." (PMID 39796040, 2024). "Under the hypoxia-hyperglycemia equation, hypoxic conditions have shown to correspond with reduced IGFBP2 levels, consequently negating the chemo-resistant effects of hyperglycemia." (PMID 34225729, 2021). "We also investigated the potential mechanism that mediated the effect of hyperglycaemia on EMT by assessing the role of IGFBP-2 and FOXA1." (PMID 32655839, 2020). "We previously published that the protective effect of hyperglycaemia in response to Docetaxel was mediated by IGFBP-2." (PMID 27754854, 2017). "IGFBP-2 abundance increased with increasing concentrations of glucose (0-25 mM) that contributed to hyperglycaemia-induced chemo-resistance as it was abrogated by downregulating IGFBP-2 using siRNA." (PMID 29088813, 2017). "Since FASN and IGFBP-2 confer resistance to chemotherapy in high glucose, reducing FASN and IGFBP-2 abundance negated the effect of hyperglycaemia under hypoxia." (PMID 29088813, 2017). "We have shown previously that hyperglycemia-induced chemoresistance in PCa cells and that this was mediated by an epigenetic upregulation of insulin-like growth factor binding protein-2 (IGFBP-2)." (PMID 29163372, 2017). "Our previous paper showed that the survival effect of hyperglycaemia was mediated by increased IGFBP-2 that can act in both, an IGF-IR-dependent manner in PC3 cells and intrinsically (independent of IGF interaction) in DU145 and LNCaP cells." (PMID 27754854, 2017). "The hyperglycaemia-induced chemo-resistance was negated by hypoxia and this was consistent with a reduction in IGFBP-2 levels." (PMID 29088813, 2017). "In this study, we examined the effect of some of the exposures associated with disturbed metabolism on TMPRSS2-ERG gene fusion, in particular, hyperglycemia and the potential role of IGFBP-2 in the latter." (PMID 29163372, 2017). "Our data suggest that hyperglycemia-induced IGFBP-2 increased the frequency of the gene fusion that was accompanied by decreased levels of DNAPKcs implying that they were mediated by alterations in the rate of repair of double-strand breaks." (PMID 29163372, 2017). "In our study, we present data showing that metformin can act in an LKB1-AMPK-independent way to induce prostate cancer cell death and counter hyperglycaemia-induced chemoresistance and that these effects involve the regulation of IGFBP-2." (PMID 27754854, 2017). "Moreover, low expression levels of IGFBP-2 at the adipose tissue mRNA and its circulating protein levels are connected to hyperglycemia and hypertriglyceridemia and positively correlate with insulin sensitivity." (PMID 37891752, 2023). "However, further research is necessary to fully understand the molecular nature of IGFBP2’s role in chemo-resistance, particular within the hypoxia-hyperglycemia crosstalk." (PMID 34225729, 2021). "This shows that a different mechanism in which hyperglycaemia activates the EMT program was involved: one of which could be through the regulation by IGFBP-2." (PMID 32655839, 2020). "IGF-I and hyperglycaemia-induced FOXA1/IGFBP-2 play important roles in EMT." (PMID 32655839, 2020). "Having shown previously that IGFBP-2 is also regulated by hyperglycaemia we investigated if these two molecules might regulate EMT in prostate cells exposed to high levels of glucose." (PMID 32655839, 2020).
Hyperglycemia (continued). "Does the glucose-induced increase in IGFBP-2 contribute to hyperglycaemia-induced chemo-resistance?" (PMID 29088813, 2017). "In addition, Akt activation increased in 25mM glucose, and this is consistent with the increase of IGFBP-2 seen in hyperglycaemia." (PMID 29088813, 2017). "Understanding the balance between hypoxia and hyperglycaemia during malignant transformation is important in identifying potential mechanistic targets/biomarkers: one of which could be IGFBP-2." (PMID 29088813, 2017). "Apart from IGFBP-2, an increase in the level of FOXA1 by hyperglycaemia in prostate cell lines was also observed in this study." (PMID 32655839, 2020). "The hyperglycaemia-induced chemo-resistance and increases in FASN and IGFBP-2 were negated in a hypoxic environment, with levels of cell death unaffected by glucose concentrations." (PMID 29088813, 2017). "After IGFBP2 was silenced with small interfering RNA (siRNA), hyperglycemia no longer conferred tumor cells the resistance to chemotherapy drugs." (PMID 31337431, 2019).
colon cancer (12 papers, 1997 to 2023). "In patients with colon cancer, higher serum concentrations of IGFBP-2 are associated with neoplastic changes in the higher levels of carcinoembryonic antigen (CEA) and colon." (PMID 37719843, 2023). "High expression of EGFR or IGFBP2 was associated with poor prognosis while high expression of SRC or SRC_pY527 predicted superior survival in colon cancer." (PMID 33758598, 2021). "Colon cancer cell lines most often secrete IGFBP-2 and it is frequently overexpressed in CRC tissues, especially glandular." (PMID 36013453, 2022). "We conclude that IGFBPs are synthesized and secreted by cells of the colonic mucosa but that proteolysis of secreted IGFBP-2 occurs in colon cancer tissue." (PMID 9218734, 1997). "However, an increased expression of IGFBP-2 mRNA in colon cancer cells and tissue is accompanied by an increased proteolytic degradation, calling for further investigations to define its potential local role in CRC." (PMID 36013453, 2022). "Also, the interaction between 25(OH)D and IGFBP2/IGFBP5 was statistically significant for colon cancer." (PMID 31434255, 2019). "This suggested exogenous IGFBP-2 inhibited cell growth by sequestering endogenous IGFs and was no longer able to do this in the presence of NBI-31772, which implied an IGF-dependent action of the exogenously added IGFBP-2 on T24 cell proliferation which has been reported in colon cancer." (PMID 31903164, 2019). "Nevertheless, the function and mechanisms of IGFBP2 in colon cancer remains unclear." (PMID 33758598, 2021). "At the functional level, the downregulation of IGFBP2 resulted in reduced migration of SW620 cells; similar findings have recently been shown using other colon cancer cells." (PMID 34830078, 2021). "In this study, we established a novel proteomic signature (including EGFR, IGFBP2, SRC and SRC_pY527) for prognostic prediction of colon cancer using TCPA database." (PMID 33758598, 2021). "Pro proliferative action of IGFBP2 has been reported in prostate, ovarian and colon cancer cells and non-transformed rat osteoblasts." (PMID 23767917, 2013). "Colon cancer extracts were able to degrade exogenous IGFBP-2, IGFBP-3 and IGFBP-4, whereas normal tissue extracts were without effect on IGFBP-2." (PMID 9218734, 1997).
heart failure (12 papers, 2018 to 2025). Inability of the heart to pump blood at an adequate rate to meet tissue metabolic requirements. "Increased IGFBP-2 levels are associated with disease severity and adverse outcomes, particularly in patients at risk for heart failure and pulmonary arterial hypertension, due to its critical role in vascular remodeling and systemic inflammation." (PMID 40278353, 2025). "Previous proteomics studies have indicated a negative correlation between IGFBP2 levels and LVEF and proposed IGFBP2 as a candidate diagnostic biomarker for heart failure and a strong prognostic factor for cardiovascular mortality." (PMID 34737791, 2021). "In this particular context, IGFBP-2 has been previously linked to cardiovascular diseases that might clinically present with AF, including heart failure and cardiomyopathy." (PMID 38673963, 2024). "Beyond oncology, elevated IGFBP-2 levels have been correlated with disease severity and mortality in conditions like heart failure and acute coronary syndrome." (PMID 39585162, 2024). "Although IGF-1 and IGFBP-2 are known to be predictors for mortality in patients with heart failure, their use in clinic as prognostic biomarkers for acute coronary syndrome (ACS) requires investigation." (PMID 36970368, 2023). "Several biomarkers—including IGFBP-1, IGFBP-2, IGFBP-3, FGF-23, MMP-2, MMP-7, TIMP-2, and RAGE/AGE—were significantly elevated in patients with cardiac involvement and independently associated with either heart failure decompensation or death/transplantation." (PMID 41226753, 2025). "IGFBP-2 has been found to be expressed in the brain, contributing to neurotrophic and regenerative functions, as well as in the heart and the serum of patients with heart failure." (PMID 38673963, 2024). "IGFBP-2 has been investigated as a biomarker for cardiovascular disease (CVD), heart failure, and cancer." (PMID 40278353, 2025). "Finally, elevated IGFBP2 inhibits IGF-1, which regulates LV dysfunction and is a biomarker for predicting heart failure." (PMID 33810615, 2021). "Notably, two proteins only detected in the miCF secretome, insulin-like growth factor binding protein 2 (IGFBP2) and osteoprotegerin (OPG), have already been reported as prognostic biomarker in human heart failure and additional cardiovascular events, respectively." (PMID 40301568, 2025).
dementia (11 papers, 2020 to 2025). Loss of intellectual abilities interfering with an individual's social and occupational functions. "For example, IGFBP2 is associated with biomarkers of AD, and elevated concentration of circulating IGFBP2 was linked with an increased risk of both all-cause dementia and AD." (PMID 33673334, 2021). "Result from the Framingham Heart Study Offspring cohort showed elevated circulating IGFBP-2 levels increased the dementia risk with a relatively large effect size (RR=2.89, 95% CI=1.63-5.13)." (PMID 33104518, 2020). "The positive correlation between IGFBP‐2 and MAS‐1 expression is noteworthy, as higher IGFBP‐2 has been correlated with increased all‐cause mortality risk in multiple human aging cohorts and predicts an increased rate of incident AD and dementia." (PMID 40264357, 2025). "Moreover, high plasma levels of IGFBP2 have been shown to predict the risk of MCI conversion to dementia." (PMID 37175824, 2023). "The elevated expression of IGFBP-2 and IGFBP-5 in the brain is of both all-cause dementia and Alzheimer’s disease." (PMID 38473707, 2024). "THPO, an activating cytokine, has been proposed to act early in dementia, and insulin-like growth factor binding protein-2 (IGFBP2) plays a modifying role." (PMID 37759795, 2023). "IGFBP-2, the most predominant IGFBP in the brain, is the only blood biomarker in HPS axis associated with dementia risk." (PMID 33104518, 2020). "Interestingly, six proteins (NEFL, WNT9A, IL17D, IGFBP2, KLK4, and PGF) were repeatedly selected in both diagnostic models that classified dementia from both cognitively normal controls and MCI." (PMID 37175824, 2023). "IGFBP2 has been reported as a potential biomarker, particularly for AD, and we found that IGFBP2 expression levels were higher in participants with dementia than in those with MCI or cognitively normal participants, and it had a moderately negative association with cognitive performance scores." (PMID 37175824, 2023). "In this study, we found the increased risk of dementia or cognitive decline could be predicted by a dropped blood concentration of TSH or DHEAS, as well as an elevated blood concentration of free-T4, SHBG, or IGFBP-2." (PMID 33104518, 2020). "Notably, NEFL, WNT9A, IL17D, IGFBP2, KLK4, and PGF proteins were included in both models that differentiated dementia from either cognitively normal controls or MCI." (PMID 37175824, 2023).